CTLA4 (cytotoxic T-lymphocyte associated protein 4)
Diseases named in the same sentence as CTLA4 in open-access papers (continued):
Sharing a sentence is not in itself a finding about the gene and the disease.
Pruritus (9 papers, 2017 to 2026). Pruritus is an itch or a sensation that makes a person want to scratch. "Meanwhile, the combination of anti-PD-1 (nivolumab) and anti-CTLA-4 (ipilimumab) agents was associated with an increased occurrence of pruritus in cancer patients." (PMID 39795946, 2024). "In summary, we identified that PD-1/-L1 inhibitor is associated with decreased risk of pruritus and rash in comparison to CTLA-4 inhibitor in both monotherapy and combined immunotherapy regimens." (PMID 34447305, 2021). "Pruritus associated with ipilimumab is believed to be a direct result of inhibiting CTLA4 and the resulting enhanced immune system activation in the skin through amplified T cell recognition of self-antigens." (PMID 33634154, 2021). "We first compared ICI monotherapy to placebo, and both PD-1/-L1 and CTLA-4 inhibitor were associated with increased risk of any grade pruritus and rash." (PMID 34447305, 2021). "PD-1/-L1 plus CTLA-4 inhibitor was associated with increased risk of pruritus (1.76 and 0.98 relative risk respectively) and rash (1.72 and 1.37 relative risk respectively) compared to either monotherapy." (PMID 34447305, 2021). "The risk of pruritus (2.15 and 4.21 relative risk respectively) and rash (1.61 and 3.89 relative risk respectively) developing from CTLA-4 or PD-1/-L1 inhibitor were increased compared to placebo, but this effect was not dose-dependent." (PMID 34447305, 2021). "Compared with CTLA-4 inhibitor, PD-1/-L1 inhibitor had a significantly decreased risk of pruritus and rash in both monotherapy and combination therapy (0.65 and 0.29 relative risk respectively)." (PMID 34447305, 2021). "PD-1/-L1 plus chemotherapy was associated with decreased risk of any grade pruritus and any grade rash, compared to CTLA-4 plus chemotherapy." (PMID 34447305, 2021). "Pruritus with anti–CTLA-4 therapy has been described to be directly associated to the inhibition of the receptor and the enhancement and activation of the immune system in the skin (Fischer, Rosen, Ensslin, Wu, & Lacouture, 2013)." (PMID 29900022, 2017). "Pruritus is one of the most common cutaneous side effects observed in cancer patients treated with either programmed cell death-1 (PD-1)/programmed cell death ligand 1 (PD-L1) or T-lymphocyte-associated antigen-4 (CTLA-4) inhibitors." (PMID 39795946, 2024). "Both CTLA-4 and PD-1 inhibitor–induced rashes may be associated with pruritus." (PMID 29900022, 2017). "RRs for any grade and high grade pruritus developed after PD-1/-L1 inhibitor treatment were 0.65 (95%CI 0.56-0.75, p < 0.00001) and 0.15 (95%CI 0.03-0.89, p = 0.04) respectively compared to CTLA-4 inhibitor treatment." (PMID 34447305, 2021). "Indeed, clinical studies demonstrate that pruritus may occur in 11–21% of patients treated with anti-PD-1/-L1 inhibitor, 24.4–35.4% of patients treated with CTLA-4 inhibitor, and 33.2–47% of patients in dual CTLA-4/PD-1 blockade." (PMID 34447305, 2021). "RRs for pruritus and rash developed after PD-1/-L1 inhibitor were decreased compared to CTLA-4 inhibitor, which is in line with the current mainstream consensus that CTLA-4 inhibitor is more likely to lead to pruritus and rash." (PMID 34447305, 2021). "Only any grade rash was more frequent in patients administered CTLA-4 inhibitor combined with PD-1/-L1 inhibitor, in comparison to CTLA-4 inhibitor monotherapy [any grade pruritus RR:0.98 (95% CI 0.80-1.19, p = 0.81), any grade rash RR:1.37 (95% CI 1.07-1.74, p = 0.01)]." (PMID 34447305, 2021).
angiosarcoma (8 papers, 2019 to 2024). A malignant tumor arising from the endothelial cells of the blood vessels. "We previously reported whole-exome and RNA sequencing results for a patient with cutaneous angiosarcoma who had a complete response to very low dose cytotoxic T-lymphocyte-associated protein 4 (CTLA-4) inhibition on a phase 1 clinical trial." (PMID 35582530, 2022). "A patient in his 40s with splenic angiosarcoma metastatic to the liver underwent splenectomy, chemotherapy, and partial hepatectomy before being treated on a clinical trial with CTLA4 and PD1 inhibitors." (PMID 38779675, 2024). "Additionally, cytometric analysis for programmed cell death protein 1 (PD1), programmed death-ligand 1 (PDL1), and cytotoxic T-lymphocyte-associated antigen 4 (CTLA4) was also performed; a study seldom investigated for angiosarcomas but may have advantages over immunohistochemical analysis." (PMID 35911262, 2022). "In this series, we report intriguing evidence of efficacy of ICIs in patients with angiosarcoma, including the first report of a complete response in a patient with cutaneous angiosarcoma treated with CTLA-4 inhibition as monotherapy." (PMID 31395100, 2019). "Based on the remarkable activity of ICIs in angiosarcoma patients, we performed exploratory analysis of immune and genetic features of patient 3 who achieved CR on a Phase I clinical trial of anti-CTLA4 antibody AGEN1884 (NCT02694822)." (PMID 31395100, 2019). "To our knowledge, we report the first complete response in angiosarcoma to CTLA-4 monotherapy." (PMID 31395100, 2019). "One cutaneous angiosarcoma patient even demonstrated a complete response to low-dose AGEN1884 monotherapy, an anti-CTLA-4 antibody." (PMID 35327375, 2022). "An ORR of 25% to dual anti-CTLA4 and anti-PD-1 blockade was reported in a phase II trial containing nine cutaneous and seven non-cutaneous metastatic or unresectable angiosarcoma patients." (PMID 35327375, 2022). "We have treated seven angiosarcoma (AS) patients with checkpoint inhibitors either in the context of clinical trials or off label [Pembrolizumab + Axitinib (NCT02636725; n = 1), AGEN1884, a CTLA-4 inhibitor (NCT02694822; n = 2), Pembrolizumab (n = 4)]." (PMID 31395100, 2019).
atopic dermatitis (8 papers, 2014 to 2025). "Similarly, cytotoxic T-lymphocyte-associated protein 4 (CTLA-4), another inhibitory receptor, has been shown to suppress pathogenic T cells in an atopic dermatitis mouse model." (PMID 41156043, 2025). "This group observed an increased level of miR-155 and decreased level of CTLA-4 in effector T-cells of patients with atopic dermatitis, suggesting that miR-155 inhibition of CTLA-4 contribute to activation of effector T-cells in the skin." (PMID 29354135, 2017). "Recently, miR-155 was shown to be overexpressed in tissues of patients with atopic dermatitis, associated with inflammatory CD4+ T cells and capable of targeting CTLA-4." (PMID 25090912, 2014).
autoimmune hemolytic anemia (8 papers, 2017 to 2025). Autoimmune hemolytic anemia (AIHA) is an autoimmune disorder in which various types of auto-antibodies are directed against red blood cells causing their survival to be shortened and resulting in hemolytic anemia. "This study characterizes a novel CTLA-4 deletion variant identified in a pediatric case of refractory autoimmune hemolytic anemia (AIHA), with the aim of delineating the clinical profile and elucidating the underlying pathogenic mechanism." (PMID 41346581, 2025). "Clinical and immunological phenotypes in DEF6-mutated patients include T-cell lymphopenia, low class-switched B cells, hepatosplenomegaly, autoimmune hemolytic anemia and bowel inflammation, all of which are reminiscent of CTLA-4 haploinsufficiency and LRBA deficiency." (PMID 31308374, 2019). "Autoimmune haemolytic anaemia (AIHA) has been associated with the use of ICPI including PD-1, PD-L1 and CTLA-4 directed antibodies." (PMID 33228219, 2020). "It has also been reported that monogenic defects may be identified in more that 2/3rd of all patients with Evans syndrome (autoimmune haemolytic anaemia and thrombocytopenia) especially defects in LRBA and CTLA-4 gene." (PMID 35795667, 2022).
autoimmune hypophysitis (8 papers, 2015 to 2025). "Visual impairments due to pituitary enlargement were more common in primary hypophysitis, which supports the concept that hypocortisolism in IIH is not primarily caused by compression of corticotroph cells, but possibly by the CTLA-4 pathway’s involvement." (PMID 36983597, 2023). "Finally, the cytotoxic T-lymphocyte 4 antigen (CTLA-4) is expressed in pituitary, and antibodies against this target induce autoimmune hypophysitis." (PMID 36766627, 2023). "Most frequently, autoimmune hypophysitis and thyroidits is encountered with anti-CTLA-4 treatment." (PMID 26981243, 2016). "Thus our results provide a tentative mechanism of how CTLA-4 blockade induces autoimmune hypophysitis and may point to a new venue of therapy development for autoimmune hypophysitis." (PMID 28262761, 2017).
basal cell carcinoma (8 papers, 2022 to 2025). A carcinoma involving the basal cells. "The current DART cohort assesses the outcome of dual low-dose anti-CTLA-4 therapy and anti-PD-1 therapy, specifically utilizing the combination of ipilimumab and nivolumab, in the management of patients with metastatic basal cell carcinoma." (PMID 39856213, 2025). "We report the basal cell cancer (BCC) cohort of the SWOG/NCI 1609 Dual Anti-CTLA-4 & Anti-PD-1 blockade in Rare Tumors (DART), a phase II prospective, multicenter basket trial of nivolumab and ipilimumab." (PMID 39856213, 2025).
biliary tract cancer (8 papers, 2021 to 2025). "Biliary tract cancer exhibits immunogenic features, including expression of the immune checkpoint molecules programmed death ligand 1 (PD-L1) and cytotoxic T-lymphocyte-associated protein 4 (CTLA-4) in the tumor microenvironment." (PMID 40868170, 2025). "Other checkpoints, such as B7-H4 and FOXP3, are associated with poor prognosis, while CTLA-4 expression in certain biliary tract cancer subtypes has shown mixed outcomes, including improved disease-free intervals in hilar biliary tract cancer." (PMID 40013133, 2025). "Gene expression studies indicate that hypermutated biliary tract cancer tumors frequently exhibit increased checkpoint molecule expression, such as CTLA-4, PD-L1, and LAG3, actively suppressing the immune response." (PMID 40013133, 2025). "The use of anti-PD-1 or anti-CTLA-4 inhibitors in biliary tract cancer is uncommon and demonstrates limited efficacy." (PMID 39839773, 2024). "As with HCC, PD-1 and CTLA-4 ICIs are currently the most studied forms of immunotherapy in patients with biliary tract cancers." (PMID 34440865, 2021). "In recent years, researchers have conducted in-depth studies on IRGs that lead to differences of immune infiltration in biliary tract cancers, and found that CTLA4 could affect chemotherapy resistance and prognosis through activation of Treg cells." (PMID 33763372, 2021). "Compared with PD-1, the benefit of CTLA-4 blockade for biliary tract cancers is poorly understood." (PMID 34440865, 2021). "Ongoing clinical trials in advanced biliary tract cancer patients reported that patients responded to ICI monotherapies with anti-programmed cell death ligand-1 (PD-L1), anti-programmed cell death protein-1 (PD-1), and anti-cytotoxic T lymphocyte-associated antigen-4 (CTLA-4)." (PMID 35163489, 2022).
Crohn disease (8 papers, 2009 to 2024). A gastrointestinal disorder characterized by chronic inflammation involving all layers of the intestinal wall, noncaseating granulomas affecting the intestinal wall and regional lymph nodes, and transmural fibrosis. "This notion is supported by the observation that genetic changes in CTLA-4 is associated with an early onset of Crohn’s disease." (PMID 35784333, 2022). "Six polymorphisms within the CTLA4 region were investigated in 333 patients with Crohn's disease and 482 unrelated healthy controls, all Caucasians of Czech origin." (PMID 20537165, 2010). "CTLA-4 inhibition disrupts mucosal self-tolerance by depleting regulatory T-cells in the gut, and genetic factors like CTLA-4 polymorphisms may increase the risk of early-onset Crohn’s disease." (PMID 39682118, 2024). "Rather the T1DM-Chrohn’s association is driven by different genes sharing common pathways such as CTLA4 and INS, or HLA-DRB1 with genes others than itself, which are genes of the HLA complex genes associated with both T1DM and Crohn’s disease." (PMID 31072055, 2019). "No crude associations with Crohn's disease were found for the tested CTLA4 variants under the log-additive or dominant models." (PMID 20537165, 2010). "Controversially, the CTLA-4:Ig fusion protein, Abatacept, was shown not to be clinically relevant in controlling Crohn’s Disease or ulcerative colitis in a clinical trial." (PMID 35784333, 2022).
Graves ophthalmopathy (8 papers, 2014 to 2024). An autoimmune disorder of the EYE, occurring in patients with Graves disease. "The G allele of rs231775 in CTLA-4 is associated with Vogt-Koyanagi-Harada (VKH) syndrome and thyroid-associated ophthalmopathy, and the G allele of rs3087243 in CTLA-4 is associated with scleritis." (PMID 33717091, 2021). "Also many studies showed the association between the CTLA4 exon-1 49A/G polymorphism and the risk of developing Graves' ophthalmopathy (GO) in GD patients." (PMID 25121088, 2014). "The present study was designed to investigate the expression of mRNA of the immune regulatory molecules FOXP3, CTLA-4/CD28/CD80/CD86, and CD40/CD40L in the orbital tissues from patients who underwent orbital decompression due to Graves' orbitopathy to assess their role in the inflammatory process." (PMID 25653477, 2015).
helminth infections (8 papers, 2007 to 2024). "In helminth infections, such as lymphatic filariasis, the expansion of CTLA-4+ T cell populations in was associated with suppressed T cell function." (PMID 22087344, 2011). "Helminth infections, including B. malayi infections, produce exhausted T cells with increased expression of inhibitory receptors (PD-1, LAG3, CTLA4) that are capable of downregulating T-cell proliferative responses and increasing the potential for apoptosis." (PMID 39434874, 2024). "Helminth infection modulates host T cell function through multiple factors including induction of Tregs, IL-10/TGF-β regulatory cytokines, PD-1/PD-L, and other co-inhibitory molecules such as LAG-3, BTLA-4, CTLA-4, Tim-3, etc.." (PMID 30093899, 2018). "Notably, anti-CTLA-4 mAb administration also induced an increase in the Th2 cytokines IL-4 and IL-5, supporting both that Tregs mediate schistosomiasis pathogenesis, and that CTLA-4 regulates the Th2 response to worm infection." (PMID 31134084, 2019).
hepatitis C (8 papers, 2009 to 2024). "Some previous studies also indicated that PDCD1, CTLA4, and HAVCR2 polymorphisms were sex-dependently associated with MAC-LD risk, the resolution of hepatitis C virus infection, and the outcomes of HCV infection, respectively." (PMID 38723011, 2024). "Increased proliferation was similarly observed with PD1+ CTLA-4+ CD8 T cells, which were isolated from the liver of hepatitis C-infected patients and stimulated with peptide in the presence of anti-PD-L1 and anti-CTLA-4 blocking antibodies." (PMID 24212939, 2011). "Taken together, CTLA-4 expression is induced early with PD-1 in HCV-specific CD8 T cells during acute hepatitis C but becomes compartmentalized to the liver with chronic infection." (PMID 19247441, 2009). "We show that CTLA-4 is preferentially co-expressed in PD-1high CD8 T cells (particularly HCV-specific CD8 T cells) in peripheral blood during acute hepatitis C and in the liver during chronic HCV infection." (PMID 19247441, 2009). "The role of CD28 in the functional response to PD-1/CTLA-4 blockade was further examined in an HLA-A2+ patient with acute hepatitis C using an HLA-A2/peptide tetramer." (PMID 19247441, 2009). "The effect of PD-1/CTLA-4 blockade was examined in 2 HLA-A2+ patients (A29, A35) with acute hepatitis C characterized by markedly elevated serum alanine aminotransferase (sALT) activities and viral titers." (PMID 19247441, 2009). "Furthermore, a blockade of one or more coinhibitory receptors (e.g., CTLA-4) can enhance virus-specific T cell function in hepatitis C virus infection." (PMID 27617959, 2016). "The importance of PD1 and CTLA4 in T cell regulation has largely been studied in various chronic viral diseases, including HIV, hepatitis B, and hepatitis C. Such chronic viral diseases induce sustained PD1 and CTLA4 expression on activated T cells." (PMID 27802341, 2016). "Thus, PD-1/CTLA-4 blockade promoted a polyfunctional HCV-specific T cell response, perhaps acting beyond the inhibition of cellular apoptosis which is increased in highly PD-1+ CD8 T cells in the liver or during acute hepatitis C." (PMID 19247441, 2009).
Hypertension (8 papers, 2018 to 2025). The presence of chronic increased pressure in the systemic arterial system. "Although the temporal association between hypertension and symptom onset-coupled with rapid resolution following blood pressure control-strongly supports hypertensive encephalopathy as the primary diagnosis, a contribution from the underlying CTLA-4 variants cannot be entirely excluded." (PMID 41346581, 2025). "When treated with abatacept, a CTLA4-Ig, mice were resistant to angiotensin II–induced hypertension and vascular superoxide production." (PMID 36951464, 2023). "Considering this, herein, we investigated one non-oncology drug named meticrane (a thiazide diuretic used to treat essential hypertension), which undescribably improved the therapeutic efficacy of anti-CTLA4 in AB1-HA tumor-bearing mice." (PMID 37274234, 2023). "Herein, we investigated one non-oncology drug named meticrane (a thiazide diuretic used to treat essential hypertension), which has been reported to indescribably improve the therapeutic efficacy of anti-CTLA4 in mice with AB1 HA tumors." (PMID 37274234, 2023). "Unfortunately, in our study, CTLA-4-dependent modulation of the CD80/CD86-CD28 pathway was not able to prevent the angiotensin II-induced hypertension." (PMID 31147569, 2019).
intrahepatic cholangiocarcinoma (8 papers, 2020 to 2025). A carcinoma that arises from the intrahepatic bile duct epithelium in any site of the intrahepatic biliary tree. "Studies have shown that anti-CTLA4 antibodies can reverse drug resistance in intrahepatic cholangiocarcinoma." (PMID 40959663, 2025). "In a mouse model experiment for intrahepatic cholangiocarcinoma, the therapeutic approach involved pre-treatment with a CTLA-4 inhibitor and platinum-based chemotherapy, followed by administration of a PD-1 inhibitor." (PMID 40936907, 2025). "We used a thioacetamide (TAA)-induced intrahepatic cholangiocarcinoma (iCCA) rat model to investigate the DNA vaccine potential against CTLA4, PD-1, and PD-L1." (PMID 33255375, 2020). "Anti-CTLA4 antibody reverses resistance of the therapy in intrahepatic cholangiocarcinoma." (PMID 38245530, 2024). "Further research revealed that platinum compounds could normalize the vasculature in Intrahepatic Cholangiocarcinoma (ICC), while dual blockade of CTLA-4 and PD-1 resulted in an increased population of CD8+ T cells." (PMID 40936907, 2025).